MBOAT1 (membrane bound glycerophospholipid O-acyltransferase 1)
Description:
Acyltransferase which catalyzes the transfer of an acyl group from an acyl-CoA towards a lysophospholipid producing a phospholipid and participates in the reacylation step of the phospholipid remodeling pathway also known as the Lands cycle. Acts on lysophosphatidylserine (1-acyl-2-hydroxy-sn-glycero-3-phospho-L-serine or LPS) and lysophosphatidylethanolamine (1-acyl-sn-glycero-3-phosphoethanolamine or LPE), and to a lesser extend lysophosphatidylcholine. Prefers oleoyl-CoA as the acyl donor and 1-oleoyl-LPE as acceptor. May play a role in neurite outgrowth during neuronal differentiation (By similarity).
Synonyms: LPSAT; LPLAT 1; OACT1; MGC44669; dJ434O11.1; LPEAT1; LPLAT14; LPLAT
Tractability: Antibody: UniProt predicts a signal peptide or a membrane-spanning region. PROTAC: ubiquitination databases record sites on it; its protein half-life has been measured.
Target class: Enzyme; Transferase
Gene: Protein-coding gene on chromosome 6 (20,099,684 to 20,212,469, reverse strand). Ensembl gene ENSG00000172197.
Subcellular location: Endoplasmic reticulum membrane
Pathways (Reactome):
Metabolism: Acyl chain remodelling of PE; Acyl chain remodelling of PS
Gene Ontology:
Molecular function: 1-acylglycerophosphocholine O-acyltransferase activity; 1-acylglycerophosphoserine O-acyltransferase activity; 1-acylglycerol-3-phosphate O-acyltransferase activity; 1-acylglycerophosphoethanolamine O-acyltransferase activity; 2-acylglycerol-3-phosphate O-acyltransferase activity; 1-alkenylglycerophosphoethanolamine O-acyltransferase activity
Biological process: phosphatidylserine acyl-chain remodeling; lipid modification; phosphatidylethanolamine acyl-chain remodeling; phospholipid biosynthetic process; regulation of neuron projection development; phospholipid metabolic process
Cellular component: endoplasmic reticulum membrane; membrane
Genetic constraint (gnomAD): Loss-of-function variants: 46 observed, 47.8 expected, observed/expected ratio (o/e) 0.96, 90% interval 0.76 to 1.23. The upper end of that interval is the gene's LOEUF score, 1.23, which puts it in group 5 of 6, group 1 being the genes least tolerant of losing a copy. Missense variants: 456 observed, 513.31 expected, observed/expected ratio (o/e) 0.89, 90% interval 0.82 to 0.96. Synonymous variants: 201 observed, 194.18 expected, observed/expected ratio (o/e) 1.04, 90% interval 0.92 to 1.16.
Homologues: Orthologues: chimpanzee MBOAT1 (99% identical), macaque MBOAT1 (98% identical), pig MBOAT1 (93% identical), dog MBOAT1 (90% identical), rabbit MBOAT1 (87% identical), rat Mboat1 (84% identical), mouse Mboat1 (83% identical), guinea pig MBOAT1 (78% identical), tropical clawed frog mboat1 (63% identical), zebrafish mboat1 (56% identical), Drosophila melanogaster oys (40% identical), Caenorhabditis elegans mboa-3 (33% identical), and 1 more. Paralogues in human: MBOAT2 (53% identical), MBOAT4 (22% identical), MBOAT7 (22% identical), LPCAT3 (22% identical), PORCN (19% identical).
Diseases named in the same sentence as MBOAT1 in open-access papers:
MBOAT1 is named in the same sentence as 21 diseases in open-access papers, as found by Europe PMC text mining. Sharing a sentence is not in itself a finding about the gene and the disease. The quoted sentences say what the papers report.
breast carcinoma (2 papers, 2023 to 2024). "Collectively, these findings highlight MBOAT1 and MBOAT2 as promising targets for prostate and breast cancers." (PMID 37735316, 2023). "The research also suggests that AR and ER transcriptionally upregulate the expression of MBOAT1 and MBOAT2, respectively, and inhibition of these receptors downregulates their transcriptional expression, sensitizing prostate cancer and breast cancer cells to ferroptosis." (PMID 37735316, 2023).
endometrial cancer (1 paper, 2023). Primary or metastatic malignant neoplasm involving the endometrium (mucous membrane that lines the endometrial cavity). "MBOAT1 exhibits high expression in several female-related cancers, including ovarian, breast, and endometrial cancers, indicating that MBOAT1 may be regulated by estrogen receptor (ER) signaling." (PMID 37735316, 2023).
melanoma (1 paper, 2018). A malignant, usually aggressive tumor composed of atypical, neoplastic melanocytes. "MBOAT1 is related to lipid biosynthesis and still poorly described, while ID4 role in melanoma is more documented and may take part in phenotypic switch of melanoma cells." (PMID 29963229, 2018).
prostate carcinoma (1 paper, 2025). A carcinoma that arises from epithelial cells of the prostate gland. "As a result of the reduction of MBOAT1/2 expression, cells become sensitive to ferroptosis, which may be useful in combination with estrogen receptor (ER) and androgen receptor (AR) antagonists in the therapy of selected breast and prostate cancers." (PMID 40872573, 2025).
cancer (2 papers, 2023 to 2024). A tumor composed of atypical neoplastic, often pleomorphic cells that invade other tissues. "While the present study demonstrates the inhibitory effects of MBOAT1/2 on ferroptosis, a comprehensive examination of all LPLATs and their modulation by cancer signaling mechanisms is yet to be undertaken." (PMID 37735316, 2023). "In the context of cancer therapy, where inhibition of MBOAT1/2 function may help unleash a pro-ferroptotic response, inhibitors of estrogen or androgen receptors may be combined with inducers of ferroptosis to achieve a more potent response." (PMID 38908072, 2024). "Subsequently, the researchers investigated the factors driving the upregulation of MBOAT1 and MBOAT2 in cancer." (PMID 37735316, 2023).
infection (1 paper, 2025). The state of being infected such as from the introduction of a foreign agent such as serum, vaccine, antigenic substance or organism. "Regulatory enzymes related to phospholipid remodeling, namely, Lpcat1, Lpcat2, and Mboat1, are also upregulated upon infection." (PMID 40463366, 2025).
kidney diseases (1 paper, 2024). "This article reviews the development of the concept of ferroptosis, the mechanisms of ferroptosis (including GSH-GPX4, FSP1-CoQ1, DHODH-CoQ10, GCH1-BH4, and MBOAT1/2 pathways), and the latest research progress on its involvement in kidney diseases." (PMID 39021564, 2024).
MBOAT1 also shares sentences with these, for which no sentence is quoted: adenocarcinoma (1 paper); amyotrophic lateral sclerosis (1); atherosclerosis (1); attention deficit-hyperactivity disorder (1); autism spectrum disorder (1); bipolar disorder (1); diabetes (1); eating disorder (1); glioma (1); Infertility (1); major depressive disorder (1); mental disorder (1); schizophrenia (1); tumor (1).